GPR137C (G protein-coupled receptor 137C)
Description:
Lysosomal integral membrane protein that may regulate MTORC1 complex translocation to lysosomes.
Synonyms: TM7SF1L2; DKFZp762F0713
Tractability: Antibody: UniProt predicts a signal peptide or a membrane-spanning region. PROTAC: its protein half-life has been measured.
Gene: Protein-coding gene on chromosome 14 (52,552,823 to 52,637,713, forward strand). Ensembl gene ENSG00000180998.
Subcellular location: Lysosome membrane
Subcellular location (Human Protein Atlas): Vesicles
Gene Ontology:
Biological process: positive regulation of TORC1 signaling
Cellular component: lysosomal membrane
Genetic constraint (gnomAD): Loss-of-function variants: 17 observed, 25.73 expected, observed/expected ratio (o/e) 0.66, 90% interval 0.45 to 0.99. The synonymous counts are far from expectation, so gnomAD's model fits this gene poorly and the ratio says little. Missense variants: 368 observed, 359.76 expected, observed/expected ratio (o/e) 1.02, 90% interval 0.94 to 1.12. Synonymous variants: 210 observed, 152.25 expected, observed/expected ratio (o/e) 1.38, 90% interval 1.23 to 1.55.
Homologues: Orthologues: chimpanzee GPR137C (99% identical), macaque GPR137C (99% identical), rabbit GPR137C (97% identical), dog GPR137C (95% identical), pig GPR137C (94% identical), guinea pig GPR137C (93% identical), mouse Gpr137c (91% identical), rat Gpr137c (91% identical), zebrafish gpr137c (55% identical), tropical clawed frog gpr137c (46% identical). Paralogues in human: GPR137B (41% identical), GPR137 (36% identical).
Diseases named in the same sentence as GPR137C in open-access papers:
GPR137C is named in the same sentence as 5 diseases in open-access papers, as found by Europe PMC text mining. Sharing a sentence is not in itself a finding about the gene and the disease. The quoted sentences say what the papers report.
gastric cancer (2 papers, 2008 to 2025). A primary or metastatic malignant neoplasm involving the stomach. "However, the regulatory mechanisms of GPR137C in the gastric cancer tumor immune microenvironment and the targeting specificity and clinical efficacy of the potential drugs require further investigation and discovery through our future research efforts." (PMID 40519905, 2025). "For example, G protein-coupled receptor 137C (GPR137C, Entrez Gene ID 283554, GCI = 3.23), a weakly annotated GPCR, is linked to a single PubMed publication associating the gene's transcription to a gastric cancer gene expression profile." (PMID 18213364, 2008).
prostate carcinoma (1 paper, 2025). A carcinoma that arises from epithelial cells of the prostate gland. "Moderate to strong cytoplasmic positivity for GPR137C was observed in prostate cancer (high, 58.33%; medium, 41.67%)." (PMID 40519905, 2025). "Here, we found that a higher expression of GPR137C (cancer-progress related isoform: ENST00000321662.10) in tumors means a poorer prognosis of prostate cancer." (PMID 40519905, 2025). "G4 drives oncogenic GPR137C to promote infiltration levels in cancer-related cells and then to contribute to the malignant progression of prostate cancer." (PMID 40519905, 2025). "Meanwhile, GPR137C protein was identified in 100% prostate cancer tissues (antibody, HP1030763)." (PMID 40519905, 2025). "In addition, it was found that GPR137C could promote migration of prostate cancer cells (C4–2 and PC3) better when compared to the Transwell assays results for si-GPR137C and wild type." (PMID 40519905, 2025). "Hence, GPR137C probably is a good druggable receptor and biomarker for prostate cancer." (PMID 40519905, 2025). "There was no weak or negative stain for GPR137C in prostate cancer." (PMID 40519905, 2025).
cancer (2 papers, 2019 to 2025). A tumor composed of atypical neoplastic, often pleomorphic cells that invade other tissues. "Our findings suggest that GPR137C is a promising independent prognostic factor and is closely associated with immune infiltration level and cancer progression in PRAD." (PMID 40519905, 2025). "Furthermore, GPR137C was found to promote infiltration levels of cancer-associated fibroblast, endothelial cells, and M2 macrophages." (PMID 40519905, 2025). "The miR-93 targets programmed cell death 1 ligand 2 (PDCD1LG2, also known as PD-L2), which is related to cancer immunotherapy, and G-protein coupled receptor 137C (GPR137C), and mitogen-activated protein kinase kinase kinase 2 (MAP3K2, also known as MEKK2) in the RAS-MAPK signaling." (PMID 30615673, 2019).
tumor (1 paper, 2025). "Then, it was found that GPR137C was not only highly expressed in tumor samples but also has high percent expression when it was compared to normal samples." (PMID 40519905, 2025). "Integrated analysis of tumor genomic heterogeneity, stemness, and the immune microenvironment revealed that combined targeted therapy against GPR137C and immunotherapy may offer greater clinical benefits for PRAD patients." (PMID 40519905, 2025). "Additionally, GPR137C likely regulates several key pathways involved in energy metabolism, cell cycle, tumor heterogeneity, and stemness in PRAD." (PMID 40519905, 2025). "Moreover, GPR137C promotes tumor microenvironment remodeling by enhancing immune cell infiltration, thereby driving PCa progression." (PMID 40519905, 2025). "In this study, we investigated the relationship between GPR137C expression and G4 structure, immune infiltration, tumor genetic heterogeneity, tumor stemness, protein interactions, and genomic alterations and analyzed GPR137C DNA methylation and small molecule drugs in PRAD." (PMID 40519905, 2025). "Meanwhile, the relationship between the expression of GPR137C and PRAD tumor cell stem was explored based on three items, i.e., differentially methylated probes-based (DMPss), DNA methylation-based (DNAss), and enhancer elements/DNA methylation-based (ENHss)." (PMID 40519905, 2025).
GPR137C also shares sentences with these, for which no sentence is quoted: lung carcinoma (1 paper).